RNU6-1285P (RNA, U6 small nuclear 1285, pseudogene)
Gene: Small nuclear RNA gene on chromosome 4 (154,543,933 to 154,544,037, reverse strand). Ensembl gene ENSG00000200350.
Homologues: Orthologues: chimpanzee U6 (97% identical), rat U6 (85% identical), dog U6 (84% identical), macaque U6 (84% identical), pig U6 (84% identical), guinea pig U6 (80% identical), mouse Gm25755 (80% identical). Paralogues in human: RNU6-21P (86% identical), RNU6-24P (85% identical), RNU6-29P (85% identical), RNU6-33P (85% identical), RNU6-39P (85% identical), RNU6-48P (85% identical), RNU6-560P (85% identical), RNU6-698P (85% identical), RNU6-890P (85% identical), RNU6-1 (84% identical), RNU6-1060P (84% identical), RNU6-116P (84% identical), and 1283 more.